GFAP (glial fibrillary acidic protein)
Diseases named in the same sentence as GFAP in open-access papers (continued):
Sharing a sentence is not in itself a finding about the gene and the disease.
Stroke (continued). "However, by day five post-stroke, in the untreated group, GSDMD was mainly present with IBA1, slightly less in GFAP, and rarely in NEUN positive cells." (PMID 39210936, 2024). "Furthermore, we investigated the correlation of stroke severity parameters and predictive factors—NIHSS score, positive “hyperdense sign”, and the combination of affected vessels, with GFAP and UCH-L1 serum levels in LVO patients." (PMID 38540221, 2024). "Post-stroke ADEV GFAP levels were elevated at D1 and D7 but not M1 compared to controls (p = 0.007, p = 0.019, and p = 0.344, respectively)." (PMID 38891912, 2024). "Despite some limitations, GFAP has been suggested to be related to traumatic brain injury (TBI) and glioblastoma multiforme, and it is a feasible strategy to identify patients with intracranial hemorrhage in the hyperacute phase of stroke." (PMID 38891912, 2024). "Another study tested a combination of UCH-L1 and GFAP in stroke patients and showed no usefulness of UCH-L1 regarding the differentiation of AIS and ICH." (PMID 38540221, 2024). "In this respect, patients from the Göttingen EPO Stroke Study that did not receive thrombolysis but were treated with erythropoietin (EPO) showed significantly lower GFAP concentrations over 7 days, suggesting a beneficial effect of EPO in patients with IS." (PMID 39459548, 2024). "The combination of a symptom-based stroke scale for stroke and LVO identification and GFAP for ICrH detection in a decision tree might enable prehospital differentiation of ICrH, AIS, LVO and stroke mimics." (PMID 36604741, 2023). "PreSS and GFAP values combined did not increase the performance for stroke subtype differentiation markedly over either GFAP or PreSS separately." (PMID 36604741, 2023). "Combined in a decision tree, GFAP and PreSS identified subgroups with high proportions of stroke mimics, ICrH, LVO, and AIS (non-LVO strokes)." (PMID 36604741, 2023). "Recovery started in the first week after stroke in WT mice (P < 0.05) but not until the third week in GFAP-C3a mice (P < 0.05)." (PMID 36995772, 2023). "In the perilesional area, they reported significant increases in GFAP+ area, compactness, and major axis length and significant decreases in form factor, solidity, and orientation in stroke subjects compared to non-stroke subjects." (PMID 37760829, 2023). "Serum and blood samples have been evaluated for GFAP determination; however, serum levels of GFAP were reported to be undetectable in some donors with IS as well as in individuals without stroke (Control, CT)." (PMID 38032374, 2023). "We also analysed the diameter of the GFAP-positive glial scar 2 and 5 weeks after stroke, and found that scar diameter decreased over time without detectable differences between vehicle and pregabalin." (PMID 36072905, 2022). "National Institutes of Health Stroke Scale (NIHSS), Hamilton Depression Scale (HAMD), Pittsburgh Sleep Quality Index (PSQI), glial fibrillary acidic protein (GFAP), and changes of norepinephrine (NE) level of patients in two groups were compared before and after treatment." (PMID 35401732, 2022). "The researchers found that serum GFAP concentration was significantly higher within the ICH group compared to the IS group 2–6 h after symptoms onset, thus highlighting the role of GFAP as an efficient tool in differentiating between the types of stroke." (PMID 36278689, 2022). "We then compared the plasma levels of D-dimer, OPN, OPG, vWF, and ADAMTS13 in LVO and non-LVO patients; the plasma levels of GFAP were compared in hemorrhagic vs. ischemic stroke and non-stroke patients." (PMID 34206615, 2021). "Furthermore, TXC treatment also increased the number of proliferating glial cells (GFAP- and BrdU-positive) in the SVZ region after 14 and 28 days post-stroke." (PMID 34212980, 2021).
Stroke (continued). "As the inflammatory process that ensues after a stroke destabilizes the BBB and contributes to neuro-axonal damage, resulting in the release of neurofilaments and glial markers into the blood, we assessed serum NF-L and GFAP levels." (PMID 33918875, 2021). "GFAP allowed to differentiate ICH from ischemic stroke and stroke mimic." (PMID 33115334, 2021). "In order to examine the phenotypic alteration of astrocytes in the co-culture with microglia, GFAP+ astrocytes were exposed to oxygen glucose deprivation (OGD) conditions, similar to the stroke microenvironment, in combination with the inflammatory cytokines TNF-α and IFN-γ." (PMID 34445510, 2021). "Serum GFAP was not significantly different between groups, whereas S100B was significantly higher in stroke patients." (PMID 33115334, 2021). "As observed for AQP4-labeling, there was no change in the length of GFAP-positive branches in Cav-1 KO stroke mice compared to sham." (PMID 32523952, 2020). "In both IR and non-IR animals after stroke, the expression of GFAP was highest close to the infarct border and significantly decreased with further distance from the lesion site." (PMID 32703986, 2020). "To characterize the perturbation of the sterile inflammatory response after stroke caused by hydrogel FBRs, we used CD13 to identify non-neural cells, GFAP to define the astrocyte border and neurofilament (NFM) to demarcate neural tissue." (PMID 33277474, 2020). "The expression of GFAP (p < 0.001) and Iba-1 (p < 0.03) was lower in the treated hyperglycemic group than in the nontreated hyperglycemic group at 6 weeks post-stroke." (PMID 31315686, 2019). "Histological analysis of a neuronal marker (Fox3), glial marker (GFAP), and neurogenesis performed 12 weeks after stroke onset did not reveal expression differences in either immunolabeling." (PMID 31507516, 2019). "Considering these previous findings and our data in this study suggesting that PTX3 promotes expression of GFAP+ astrocytes, we assessed whether PTX3 influences neuronal viability after experimental stroke." (PMID 30315331, 2018). "In contrast, GFAP levels were not decreased in MIF knockouts in an experimental stroke model and the authors concluded that MIF is part of the gliotic process but not essential for it58." (PMID 29084983, 2017). "The levels of GFAP and of antibodies against NR2 RNMDA assessed within 12 hrs after the onset of symptoms could be used to identify the type of stroke (IS or ICH) with a discriminant function – binary logit regression." (PMID 26081945, 2015). "Most of the stroke patients displayed negative GFAP and VSNL-1 in the peripheral blood during this time period, indicating that these proteins are unlikely to be released from the brain to the bloodstream during this time window of stroke." (PMID 23497639, 2013). "Instead, a HF diet significantly aggravated the induction in GFAP immunoreactivity in the peri-ischemic region specifically in ApoE3-TR and ApoE4-TR mice but not in WT mice at 3 days post stroke." (PMID 23957944, 2013). "In this study, we were able to show, that age, sex, co-morbidities, risk factors as well as the vast majority of neurological diseases, especially the classical “stroke mimics” do not critically interfere with the use of GFAP as an ICH biomarker." (PMID 23626774, 2013). "The number of astrocytes, as assessed by both glutamine synthetase (GS) and S100β immunoreactivity in the cortical penumbra following stroke does not increase strikingly over time, while GFAP and vimentin expression do." (PMID 22132159, 2011). "Under normal conditions, GFAP is not typically detected in the serum; however, in patients who have experienced a brain injury such as stroke, levels often increase secondary to reactive astrogliosis—a process characterized by the proliferation and hypertrophy of astrocytes in response to damage." (PMID 41598337, 2026).
Stroke (continued). "Optogenetic stimulation of GFAP-Arch mice led to not only a reduction in glial scar stiffness but also the increases of EdU+DCX+ and EdU+CD31+ cells, which indicated an increased capacity to promote endogenous neuro-regeneration and angiogenesis for neurological recovery after stroke." (PMID 41346705, 2026). "Significant differences were observed for the biomarkers GFAP (142.91 ± 102.19 pg/mL in patients with acute stroke vs. 37.76 ± 19.92 pg/mL in patients without stroke (p < 0.001)) and UCH-L1 (1307.68 ± 967.54 pg/mL in stroke patients vs. 189.81 ± 92.69 pg/mL in patients without stroke (p < 0.001))." (PMID 40649119, 2025). "However, at the time of writing, the LVOne has only been evaluated in a single disease state, with no previous studies conducted outside of stroke populations, using serum samples instead of plasma, or in comparison to other lab-based GFAP assays." (PMID 40650780, 2025). "For example, elevated GFAP levels may indicate a hemorrhagic stroke, while low levels may suggest the absence of such a stroke." (PMID 40649119, 2025). "When combined with clinical predictors, GFAP measurements could enhance early identification of ICH in the field, enabling the possibility of initiating targeted interventions during prehospital transfer to specialized stroke centers." (PMID 41227149, 2025). "To investigate stroke‐induced changes in pan‐lactylation across different brain cell types, we performed immunofluorescence co‐staining of pan‐Kla with markers of neurons (MAP2 or NeuN), astrocytes (GFAP or S100β), microglia (IBA1), and oligodendrocytes (Olig2 or MBP)." (PMID 40271828, 2025). "Moreover, immunofluorescence analysis showed that after intravenous injection into C57BL/6 mice at 72 h postischemic stroke, the red fluorescent DiD‐EXO‐PD‐L1‐HGF was co‐localized with glial fibrillary acidic protein (GFAP)‐ or MAP2‐expressing (green fluorescence) cells in the brain with stroke." (PMID 39049677, 2024). "After vessel occlusion, the gradual occurrence of astrocyte damage and BBB disintegration (usually not before 6 to 12 h after stroke onset) leads to a delayed release of GFAP into the plasma, not reaching peak concentrations before 48–96 h after symptoms onset." (PMID 38891912, 2024). "Additionally, this could serve as a valuable biological tool and strategy to investigate the benefits of determining GFAP and UCH-L1 levels in the blood for other neurological conditions such as severe TBI, stroke, and intracranial pressure." (PMID 38674124, 2024). "In most studies, GFAP was measured using ELISA techniques (expressed in ng/mL) or did not include stroke patients beyond the hyperacute phase, thus limiting information in acute stroke of unknown or delayed onset." (PMID 39777311, 2024). "Similarly, GFAP, S100b and NSE, among others, have been investigated as the biomarkers for stroke." (PMID 38649772, 2024). "Interestingly, CD63 expression was shown here to be significantly pronounced and co-localized with angiogenic marker VEGF compared to glial marker GFAP or neurogenic marker MAP2, suggesting that the CD63-labeled extracellular vesicles preferably mediated host angiogenesis after stroke." (PMID 38069179, 2023). "Serum levels of GFAP are low/undetectable in individuals without stroke." (PMID 36604741, 2023). "The patient cohort in this study consisted of 38% stroke mimics and GFAP could not differentiate these patients from stroke and TIA patients." (PMID 36604741, 2023). "Thus, GFAP-expressing reactive astrocytes appear as important negative regulators of neuronal functioning in the chronic phase after stroke." (PMID 36995772, 2023). "GFAP could not differentiate stroke mimics (including SDH) from AIS shown by an AUC of 0.47 (95% CI 0.40–0.55) or stroke mimics (including SDH) from stroke and TIA with an AUC of 0.54 (95% CI 0.47–0.60)." (PMID 36604741, 2023).
Stroke (continued). "The second group included two studies dealing with the possible role GFAP could play in predicting each patient’s recovery potential, while the third group consisted of four studies examining the potential link between RDW and recovery following stroke." (PMID 36278689, 2022). "To assess whether the failure of vascular remodeling caused by astrocyte ablation affected the restoration of blood flow, we used multi-exposure speckle imaging (MESI) to track blood flow after stroke (n = 8 control mice [n = 5 wild-type+GCV, n = 3 GFAP-TK+saline], n = 8 GFAP-TK+GCV mice)." (PMID 33910014, 2021). "Finally, the levels of GFAP, Iba-1, and arterial wall thickness were lower in the treated hyperglycemic group than in the nontreated hyperglycemic group at 6 weeks post-stroke." (PMID 31315686, 2019). "Importantly, the immunofluorescence analysis of the brain sections after stroke revealed several GFP-positive cells with glial morphology that were not positive for the astrocyte marker GFAP." (PMID 28253906, 2017). "Further, we did not assess differences in the level of UCH-L1 and GFAP based on stroke location." (PMID 27074724, 2016). "Additionally, immune responses against MBP and GFAP were found to be more common in stroke patients with acquired infection and had worsened outcomes compared to stroke patients without infection." (PMID 26742037, 2016). "The additional predictive ability comes from an increase in sensitivity when adding in NR2, so that by using the levels of GFAP and of NR2 RNMDA antibodies, at 12 hrs after onset, we can identify with a very good sensitivity and specificity (94% and 91%, respectively) the type of stroke." (PMID 26081945, 2015). "We reasoned that an expansion of this rare AdpNSC population might occur in an injury model such as stroke, where there is no depletion in the GFAP+ adult NSC fraction." (PMID 24936468, 2014). "However, although brain-specific, GFAP is not AD-specific, since elevated levels are also observed in other neurological conditions, such as traumatic brain injury, multiple sclerosis, and stroke, and can also be influenced by systemic inflammation." (PMID 40943483, 2025). "We subsequently evaluated whether full-length GFAP band intensities increase with neurological deficit, assessed by the NIHSS score reflecting the severity of symptoms, or correlate with short-term prognosis according to the mRS score at D7 and M1 after the stroke onset." (PMID 38891912, 2024). "Moreover, given the fact that stroke represents a rather heterogenous syndrome, a combined panel incorporating BNP, GFAP, RDW, NLR, MMP-9, and AQP4 might represent a promising approach, both in research and in clinical practice, minimizing the effect of any individual biomarker." (PMID 36278689, 2022). "Furthermore, for these patients who had the neurological deficits (two patients with stroke and one patient who died), the serum concentrations of GFAP and S100B still could not return to the baseline level even at the 30-day follow-up." (PMID 34381130, 2021). "We studied whether the serum levels of glial fibrillary acidic protein (GFAP) and of antibodies against the N-methyl-d-aspartate receptor subunit NR2 (NR2 RNMDA) can discriminate between intracerebral haemorrhage (ICH) and ischaemic stroke (IS) in stroke patients." (PMID 26081945, 2015). "After correction, GFAP and UCH-L1 remained significantly different between the stroke and without-stroke groups (adjusted p < 0.01), supporting their relevance as potential diagnostic biomarkers." (PMID 40649119, 2025). "Given that plasma GFAP and NfL are elevated not only in FTD but also in other neurological diseases such as Alzheimer disease, stroke, and TBI, these biomarkers are not anticipated to serve as FTD-specific diagnostic markers." (PMID 40075459, 2025). "We observed clear colocalization of SARM1 and NeuN in both the sham-treated and stroke-injured groups, whereas no colocalization was detected between SARM1 and Iba1 or GFAP." (PMID 41272776, 2025).
Stroke (continued). "Two days post-stroke, GSDMD predominantly colocalized with IBA1, slightly less with GFAP, and almost none with NEUN." (PMID 39210936, 2024). "Post-stroke TEV and ADEV aliquots drawn at D1 and D7 but not M1 showed a significant increase in full- length GFAP when compared to the control group." (PMID 38891912, 2024). "Four weeks post-stroke, they performed GFAP immunohistochemistry and utilized HCI to examine 19 astrocyte morphological parameters in the perilesional area and ipsilateral hemisphere of stroke and non-stroke subjects." (PMID 37760829, 2023). "Although CD13 deletion in sham mice did not enhance gliosis, however after stroke CD13KO mice had increased proliferation of Iba-1+ microglia and GFAP+ astrocytes in the peri-infarct area." (PMID 37817190, 2023). "In stroke, however, curative PHP.GFAP-IL-2 treatment after stroke induction did not reduce the resulting lesion size in either the dMCAO or photothrombotic models." (PMID 35618831, 2022). "Furthermore, the inhibitory assay showed that only the γ-secretase inhibitor of DAPT reduces GFAP levels and decreases brain infarct volume, suggesting γ-secretase appears to be a therapeutic target and its inhibitor of DAPT may have the therapeutic potential for the treatment of stroke." (PMID 36289917, 2022). "At 3 days post-stroke (PSD3), slight microgliosis (IBA-1) and astrogliosis (GFAP) was evident in thalamus, but no infarct." (PMID 34131204, 2021). "In contrast, while a transient MCAO mouse model of stroke revealed a significant decrease in GFAP expression in the cortex and striatum of iPSC-NSC-treated animals at 7 days post-stroke, a difference was not seen at 28 days post-stroke." (PMID 33796535, 2021). "The increased concentrations of GFAP and S100B in serum are more significant for patients with symptomatic stenosis (two patients had TIA, two patients had stroke, and one patient died) after CAS than the patients without complications." (PMID 34381130, 2021). "Overall, GFAP and iNOS concurred with TSPO immunohistochemistry, with no significant changes in remote WM following ET1-induced stroke." (PMID 32990808, 2020). "Ischemia induced significant upregulation of GFAP immunoreactivity in the peri-ischemic area compared to the contralateral side, yet SSO failed to reduce stroke-induced increased GFAP immunoreactivity." (PMID 29202856, 2017). "The primary findings of this study indicate that patients experiencing an acute stroke who were identified with a “stroke alert” exhibited significantly elevated serum levels of both GFAP and UCH-L1 when compared to those presenting with stroke mimics (the group without stroke)." (PMID 40649119, 2025). "Specifically, in Appalachian populations, stroke patients showed significant differences in multiple ADRD biomarkers (AB40, AB42, and GFAP) compared to controls, a pattern not seen in non-Appalachian stroke patients, where only GFAP levels increased." (PMID 41306424, 2025). "In AIS, GFAP levels appear to increase with longer delays since symptom onset and were higher in patients with more extensive ischemic changes on baseline CT (ASPECTS ≤7) than those without, particularly in LVO stroke." (PMID 39777311, 2024). "Two days post-stroke with no treatment (Group B), GSDMD-positive cells were prominently present in penumbra region near the hypoxic core, with a majority co-expressing IBA1 or GFAP, indicating expression in both microglia and astrocytes (Figures 2DA–DE)." (PMID 39210936, 2024). "Using SIMOA, we investigated the ability of GFAP to identify ICrH and further, organized in a decision tree, the ability of GFAP combined with PreSS to identify groups of patients, i.e., separating stroke mimics, ICrH, LVO, and AIS (non-LVO strokes)." (PMID 36604741, 2023).